VMAC (vimentin type intermediate filament associated coiled-coil protein)
Tractability: No criterion of Open Targets' tractability assessment is met for any kind of drug.
Gene: Protein-coding gene on chromosome 19 (5,904,872 to 5,910,853, forward strand). Ensembl gene ENSG00000187650.
Subcellular location: Cytoplasm
Gene Ontology:
Molecular function: protein binding
Cellular component: type III intermediate filament; cytoplasm
Genetic constraint (gnomAD): Loss-of-function variants: 8 observed, 2.63 expected, observed/expected ratio (o/e) 3.05. That is too few expected variants to judge how well the gene tolerates losing a copy. Missense variants: 248 observed, 184.79 expected, observed/expected ratio (o/e) 1.34, 90% interval 1.21 to 1.49. Synonymous variants: 96 observed, 80.28 expected, observed/expected ratio (o/e) 1.2, 90% interval 1.01 to 1.42.
Homologues: Orthologues: chimpanzee VMAC (99% identical), pig VMAC (87% identical), guinea pig VMAC (80% identical), mouse Vmac (76% identical), rat Vmac (51% identical), zebrafish VMAC (51% identical), tropical clawed frog vmac (38% identical).
Diseases named in the same sentence as VMAC in open-access papers:
VMAC is named in the same sentence as 4 diseases in open-access papers, as found by Europe PMC text mining. Sharing a sentence is not in itself a finding about the gene and the disease. The quoted sentences say what the papers report.
glaucoma (2 papers, 2025). Increased pressure in the eyeball due to obstruction of the outflow of aqueous humor. "As a result, ethanolamine kinase 1 (ETNK1), vimentin-type intermediate filament-associated coiled-coil protein (VMAC), nexilin (NEXN), and Sad1 and UNC84 Domain Containing 1 (SUN1) were identified as glaucoma-associated autoantibodies." (PMID 40149693, 2025). "ETNK1, VMAC, NEXN, and SUN1 were identified as glaucoma-associated autoantibodies based on their plasma levels and positive rates." (PMID 41463042, 2025). "In this study, a cohort of cataract, NTG, and POAG patients was examined by CWPA for plasma autoantibodies, and four new autoantibodies, ETNK1, VMAC, NEXN, and SUN1, were detected as glaucoma-related." (PMID 40149693, 2025).
COVID-19 (1 paper, 2021). A disease caused by infection with severe acute respiratory syndrome coronavirus 2. "ULBP2, SYT2, VMAC, and FOXJ1 followed the same pattern of expression in COPD compared to COVID-19, however, to a much lower level." (PMID 33679887, 2021).
VMAC also shares sentences with these, for which no sentence is quoted: lymphoma (1 paper); open-angle glaucoma (1).